CCNB1 (cyclin B1)
Diseases named in the same sentence as CCNB1 in open-access papers (continued):
Sharing a sentence is not in itself a finding about the gene and the disease.
membranous nephropathy (2 papers, 2016 to 2019). "In the model of membranous nephropathy report that Cdc2, cyclin B1, and cyclin B2 were increased in podocytes despite absent proliferation." (PMID 27888806, 2016). "Similarly, in other glomerular diseases, such as membranous nephropathy, a polynuclear podocyte phenotype can be found and DNA synthesis increases, as does the expression of cyclin B1 and B2, but there is no cell proliferation." (PMID 31801948, 2019).
Obesity (2 papers, 2023 to 2024). Accumulation of substantial excess body fat. "The obesity-exacerbated TNBC progression was attenuated after IF, which decreased cyclin B1 and vimentin levels and reduced the proinflammatory signature in the obesity-associated tumor microenvironment." (PMID 38999849, 2024). "On the other hand, IF targets the obesity-induced parameters, lowering body weight and blood glucose/cholesterol to destroy the obesity-associated microenvironment of TNBC with downregulated cyclin B1/vimentin and Mφ accumulation followed by decelerated TNBC progression and mortality (green arrows)." (PMID 38999849, 2024).
ovarian tumor (2 papers, 2008 to 2015). "The proliferation-related targets AURKA and CCNB1 were overexpressed in clinical ovarian tumor specimens." (PMID 26317392, 2015).
peritoneal cancer (2 papers, 2016 to 2018). A peritoneum cancer that is located in the inside of the abdomen. "To explore the possibility of using circ-Ccnb1 as an agent for cancer therapy, we developed a peritoneal cancer model by injecting cancer cells into the peritoneal cavity of mice." (PMID 29795334, 2018). "Deregulation of the expression of BAG1, CCNB1, MKI67, and MYBL2 was documented in PC biopsies, suggesting that growth and cell proliferation pathways are disturbed, a feature of malignant transformation in ovarian and peritoneal cancer that has been widely documented in the literature." (PMID 27542596, 2016).
prostate tumors (2 papers, 2014 to 2017). "Expression of SPDEF reduced the tumor burden, decreased the number of Ki67 and PH3-positive cells, and reduced mRNA levels of proliferation-specific genes Cdc25b, Cyclin B1, Cyclin A2, PLK1, CKS1, Aurora B and Topo2 alpha in the prostate tumors." (PMID 25254494, 2014).
serous ovarian cancer (2 papers, 2020 to 2025). "Similarly, a study on serous ovarian cancer cell lines demonstrated that PIK3R1 downregulation induced the expression of antiapoptotic BCL2, as well as genes involved in cell cycle progression (CCNB1) and metastasis (MMP9 and VEGFA)." (PMID 39858051, 2025).
skin cancer (2 papers, 2021 to 2022). "We applied 3-DSC to skin cancer cells before performing cell flow cytometry and western blotting using G2/M phase marker cyclin B1." (PMID 33842463, 2021).
temporal lobe epilepsy (2 papers, 2015 to 2016). A localization-related (focal) form of epilepsy characterized by recurrent seizures that arise from foci within the temporal lobe, most commonly from its mesial aspect. "This includes up-regulation of Cyclin B1 in hippocampus of pentylenetetrazole (PTZ)-kindled rats and in human patients with temporal lobe epilepsy." (PMID 26863447, 2016). "For example, cyclin B1 upregulation is observed in the hippocampus of pentylenetetrazole (PTZ)-kindled rats and patients with temporal lobe epilepsy." (PMID 25681415, 2015).
acromegaly (1 paper, 2021). Acromegaly is an acquired disorder related to excessive production of growth hormone (GH) and characterized by progressive somatic disfigurement (mainly involving the face and extremities) and systemic manifestations. "As an example, CCNB1 overexpression in acromegaly can be targeted with resveratrol, inhibiting CCNB1 and reverting its effects on invasion." (PMID 33790868, 2021).
acute lymphoblastic leukemia (1 paper, 2012). Leukemia with an acute onset, characterized by the presence of lymphoblasts in the bone marrow and the peripheral blood. "In acute lymphoblastic leukemia, SF increased the expression of Cyclin B1 in the REH, RS-4 and T-ALL cell lines." (PMID 23251470, 2012).
acute myeloid leukemia (1 paper, 2014). Acute myeloid leukemia (AML) is a group of neoplasms arising from precursor cells committed to the myeloid cell-line differentiation. "FOXM1 and its targets such as Cyclin B1 have been implicated in promoting proliferation through modulating cell cycle progression in acute myeloid leukemia (AML)." (PMID 25365263, 2014).
asthma (1 paper, 2025). "Despite these limitations, our study identifies seven core targets (HSP90AB1, CCNB1, CCK, CDK6, CASP9, NR3C1, and ERBB2) that offer promising avenues for developing novel asthma therapies." (PMID 41403444, 2025).
B-cell lymphomas (1 paper, 2017). "A positive correlation between Bcl-6 and cyclin A or cyclin B1 expression has previously been reported for B-cell lymphomas where Bcl-6 promotes cell proliferation." (PMID 27880939, 2017).
basal cell carcinoma (1 paper, 2015). A carcinoma involving the basal cells. "Shh signaling, driven exclusively by PTCH1 that is SMO/GLI1-independent, includes induction of apoptosis in endothelial and neuroepithelial cells and regulation of the Cyclin B1/CDK1 pathway in basal cell carcinoma." (PMID 26545965, 2015).
cervical squamous cell carcinoma (1 paper, 2024). A squamous cell carcinoma arising from the cervical epithelium. "Current research has implicated CCNB1 in the pathogenesis of various cancers, such as gastric, pancreatic, and cervical squamous cell carcinomas." (PMID 38581717, 2024).
childhood asthma (1 paper, 2025). "The diagnostic and prognostic value of lncRNAs is gaining traction, with the PTTG3P/miR-192-3p/CCNB1 axis emerging as a potential biomarker for childhood asthma, underscoring their promise in non-invasive disease monitoring." (PMID 40806181, 2025).
colitis (1 paper, 2016). Inflammation of the colon. "Interestingly, RIPK3-deficient mice had increased Wnt-β-catenin signaling shown by induction of genes important for IEC survival, proliferation and invasiveness (cMyc, Cox2 and Wisp1), and cell cycle progression (Cyclin B1, Cyclin D1, Cyclin E and p21) during colitis-associated CRC." (PMID 27344176, 2016).
cutaneous melanoma (1 paper, 2019). A primary melanoma arising from atypical melanocytes in the skin. "Our experiments showed that ESC microenvironment had the ability to inhibit proliferation and enhance apoptosis of cutaneous melanoma cells, coinciding with down‐regulation of Cyclin D1 and Cyclin B1, which resulted in a reduction in the percent of cells in G0/G1." (PMID 31173492, 2019).
cystadenocarcinoma (1 paper, 2004). A malignant cystic epithelial neoplasm arising from the glandular epithelium. "In the cystadenocarcinomas, there was occasional coexpression of cytoplasmic cyclin B1 with nuclear phosphohistone H3 (approx 1% of phosphohistone H3-positive cells), most likely representing cells around the G2/M transition." (PMID 15083189, 2004). "Cyclin A and cyclin B1 LIs were elevated in borderline tumours compared to cystadenomas (P=0.003 and <0.0001, respectively) and in serous cystadenocarcinomas compared to borderline tumours (P=0.001 and <0.0001, respectively)." (PMID 15083189, 2004).
depression (1 paper, 2023). "The pathogenesis of depression was associated with changes in SPP1, Plasminogen activator inhibitor 1, CCNB1 protein, CCL3, and other genes." (PMID 37932972, 2023). "We screened depression-related DEGs in the GEO database and combined them with the TCMSP database in this study and concluded that the occurrence of depression was closely related to changes in SPP1, SERPINE1, CCNB1, CCL3, and other genes." (PMID 37932972, 2023).
focal segmental glomerulosclerosis (1 paper, 2017). A renal disorder characterized by sclerotic lesions in the glomeruli. "For example, in the cellular type of human FSGS (focal segmental glomerulosclerosis), studies have found absent p27, p57, and cyclin D1 expression and increased cyclin E, cyclin A, cyclin B1, CDK2, and p21." (PMID 28164134, 2017).
gallbladder carcinoma (1 paper, 2023). "Gene expression heat map showed that KNTC1, MCM2, CKAP2, RACGAP1, CCNB1 were highly expressed in gallbladder carcinoma samples." (PMID 37480569, 2023). "We found that five core genes (KNTC1, MCM2, CKAP2, RACGAP1, CCNB1) were highly expressed in gallbladder carcinoma samples and low in normal samples." (PMID 37480569, 2023).
gastric adenocarcinoma (1 paper, 2025). "Notably, gastric adenocarcinoma uniquely exhibits G2/M arrest via cyclin B1/survivin suppression, highlighting the pleiotropic mechanisms of fucoxanthin." (PMID 40735485, 2025).
gastroenteropancreatic neuroendocrine tumors (1 paper, 2012). "More recently, GTSE1 was identified as one of three cell cycle regulatory genes (along with CDKN3 and Cyclin B1) whose upregulation in gastroenteropancreatic neuroendocrine tumors correlate with metastasis." (PMID 23236459, 2012).
gestational diabetes (1 paper, 2025). Carbohydrate intolerance first diagnosed during pregnancy. "Subsequent research will delve into the effects of reducing CCNB1 on additional essential metabolic controllers like AMPK, HK2, and FASN, in order to gain a more comprehensive understanding of its broader involvement in metabolic control during gestational diabetes." (PMID 39822992, 2025).
gynecological cancer (1 paper, 2008). "Uncontrolled expression of cyclin B1 is associated with neoplastic transformation and gynecological cancer development." (PMID 19113992, 2008). "Collectively, downregulation/depletion of cyclin B1 worked effectively in all gynecological cancer cell lines tested." (PMID 19113992, 2008). "In the present study, we focus on gynecological cancer cell lines and investigate the effect of small interfering RNA (siRNA) induced cyclin B1 knockdown on tumor cell proliferation." (PMID 19113992, 2008). "Our data support the notion of cyclin B1 being essential for survival and proliferation of gynecological cancer cells." (PMID 19113992, 2008). "The data suggest that specific targeting of cyclin B1 could sensitize some gynecological cancer cells, like MCF-7 and MDA-MB-231 cells, to conventional chemotherapeutic agents like taxol, thereby reducing their side-effects by lowering their dosage." (PMID 19113992, 2008).
HCMV infection (1 paper, 2014). "Whereas Cyclin D1 expression was largely unaffected by HCMV infection and all four viruses led to a strong and sustained induction of Cyclin E1, they markedly differed with respect to Cyclin A2, Cyclin B1 and APC5 protein regulation." (PMID 25393019, 2014).
Hepatitis B (1 paper, 2022).
hyperthyroidism (1 paper, 2021). Overactivity of the thyroid gland resulting in overproduction of thyroid hormone and increased metabolic rate. "A total of 112 genes related to R. Scrophulariae and hyperthyroidism were obtained, and these included PTEN, EP300, and CCNB1." (PMID 34650432, 2021).
Hypoglycemia (1 paper, 2023). A decreased concentration of glucose in the blood. "The purpose of this docking was to investigate whether the primary bioactive constituents of the compound played a role in hypoglycemia through the compound's key targets, which were CDK2, E2F1, CDKN1A, CDK1, and CCND1 and CCNB1." (PMID 36846049, 2023).
injury (1 paper, 2024). Damage inflicted on the body as the direct or indirect result of an external force, with or without disruption of structural continuity. "In this study, we found that the HuR protein expression was inducible in the mouse model of APAP‐induced liver injury and found that HuR could protect against APAP‐induced liver injury by promoting the expression of NRF2, cyclin A1, cyclin B1, cyclin D1, CDK2, ATG3, ATG5 and ATG7." (PMID 39614424, 2024).
insulinoma (1 paper, 2016). "Other groups also observed increased cyclin B1 and D2 levels in MAFB-overexpressing insulinoma cells, and this was verified in our experiments." (PMID 27829226, 2016).
Kashin-Beck disease (1 paper, 2022). Disabling osteochondrodysplasia with osteosclerosis, cone-shaped metaphysis, and shortening of the diaphysis. "Furthermore, compared to normal controls, CCNB1 protein in Kashin-Beck disease articular cartilage was 71.98% and 66.27% downregulated in the superficial and middle zones, respectively, and 12.06% upregulated in the deep zone." (PMID 36588792, 2022). "The purpose of this study was clarify the relationship between the differential expression of cyclins CCNB1 and CCNG1 and chondrocyte damage in Kashin-Beck disease." (PMID 36588792, 2022). "Finally, the protein expression levels of CCNB1 and CCNG1 were verified in knee cartilage tissue of Kashin-Beck disease patients and normal controls by immunohistochemical staining." (PMID 36588792, 2022). "The differential expression of cyclins CCNB1 and CCNG1 may be related to articular cartilage damage in Kashin-Beck disease." (PMID 36588792, 2022).
keloid (1 paper, 2024). An irregularly shaped, elevated mark on the skin caused by deposits of excessive amounts of collagen during wound healing. "A fibroblast-related diagnostic model for keloid based on a six-gene signature (CCNB1, EGFR, E2F8, BTG1, TP63, and IGF1) was proposed, showing high predictive accuracy in keloid diagnosis." (PMID 39157347, 2024). "•CCNB1, EGFR, E2F8, BTG1, TP63, and IGF1 were associated with keloids." (PMID 39157347, 2024). "The established model based on CCNB1, EGFR, E2F8, BTG1, TP63, and IGF1 showed good performance and may be useful for keloid diagnosis." (PMID 39157347, 2024). "In comparison to levels in control tissues, the expression levels of CCNB1, EGFR, BTG1, as well as TP63 were evidently lower in the keloid tissues (P < 0.05), while the expression levels of E2F8 as well as IGF1 were evidently higher in the keloid tissues (P < 0.05)." (PMID 39157347, 2024). "In the training dataset, the expression levels of CCNB1, EGFR, E2F8, BTG1, as well as TP63 were remarkedly lower in the keloid samples than in the control samples (P < 0.05); however, the expression of IGF1 was evidently enhanced in the keloid samples elative to the control samples (P < 0.05)." (PMID 39157347, 2024).
Lewis lung carcinoma (1 paper, 2019).
liver fibrosis (1 paper, 2023). "Subsequently, the expression of Anln, Hmmr, Tpx2, Ccnb1, and Ccnb2 was measured in activated hepatic stellate cells (HSCs), which have been shown to become myofibroblast-like cells known to contribute to the progression of liver fibrosis through the deposition of extracellular matrix proteins." (PMID 37566034, 2023).
lung fibrosis (1 paper, 2023). "FOXM1 plays a major role in regulating the development of lung fibrosis by inducing the expression of the proliferation-related genes CCNB1, CCND1, and PLK1." (PMID 37238726, 2023).
Lynch syndrome (1 paper, 2018). An autosomal dominant hereditary neoplastic syndrome characterized by the development of colorectal carcinoma and a high risk of developing endometrial carcinoma, gastric carcinoma, ovarian carcinoma, renal pelvis carcinoma, and small intestinal carcinoma. "Whole‐genome mRNA expression profiles of 41 tumors and immunohistochemical stainings against FGFR3, KRT5, CCNB1, RB1, and CDKN2A (p16) of 37 tumors from patients with Lynch syndrome were generated." (PMID 29791078, 2018).
malignant phyllodes tumor (1 paper, 2024). A phyllodes tumor with sarcomatous stroma. "Mitotic count (No./10 HPF), expression count (No./10 HPF) of Cyclin A2, Cyclin B1, Cyclin E, and PHH3, labeling indices (%) of Ki-67 and Survivin, and a maximum diameter of each benign, borderline, or malignant phyllodes tumor." (PMID 39553132, 2024).
mesothelioma (1 paper, 2009). A usually malignant and aggressive neoplasm of the mesothelium which is often associated with exposure to asbestos. "Mesothelioma cells treated with alpha- interferon were blocked in the G2/M phase and cyclin B1/cdc2 expression was down-regulated." (PMID 19662092, 2009).
metastatic cancer (1 paper, 2023). A carcinoma which has spread from the original site of growth to another anatomic site.
metastatic disease (1 paper, 2023). "Our findings suggest that CCNB1 is a potential therapeutic target for inhibiting LVI in BC and reducing the occurrence of metastatic disease." (PMID 36418517, 2023).
neck cancers (1 paper, 2023). "In addition, CCNB1, which is aberrantly expressed in patients with breast, lung, head, and neck cancers, can be recognized by antibodies and T cells as tumour antigens." (PMID 37592341, 2023).
neuroendocrinal tumors (1 paper, 2012). "Cyclin B1 levels were significantly overexpressed in poorly differentiated tumors while Cox2 levels were significantly overexpressed in neuroendocrinal tumors." (PMID 22348039, 2012).
osteoporosis (1 paper, 2024). A condition of reduced bone mass, with decreased cortical thickness and a decrease in the number and size of the trabeculae of cancellous bone (but normal chemical composition), resulting in increased fracture incidence. "Consequently, enhancing the expression of CCNB1 or refining cell cycle regulation may bolster the proliferation of both osteoblasts and neuronal cells, thereby fostering the recovery of bone mass, decelerating the onset of osteoporosis, and alleviating the manifestations of PD." (PMID 39840278, 2024).
Overgrowth (1 paper, 2024). Excessive postnatal growth which may comprise increased weight, increased length, and/or increased head circumference. "In human gingival fibroblasts from patients experiencing gingival overgrowth due to cyclosporine A, the mRNA expression of CYCLIN B1 was higher than that in normal gingival fibroblasts from healthy individuals." (PMID 39727652, 2024).
papillary renal cell carcinoma (1 paper, 2023). A rare subtype of renal cell carcinoma, arising from the renal tubular epithelium and showing a papillary growth pattern, which typically manifests with hematuria, flank pain, palpable abdominal mass or nonspecific symptoms, such as fatigue, weight loss or fever. "PRC1 has revealed upper expression in other cancer tissues such as, among others, invasive cervical carcinomas, papillary renal cell carcinoma, pediatric adrenocortical tumour, while yet not being studied in depth as compared to CCNB1, ADAM10 or RACGAP1." (PMID 37438763, 2023).
parasite infections (1 paper, 2019). "As detected on DNA content level, parasite infections induced a G2/M cell cycle arrest without affecting expression of G2-specific cyclin B1." (PMID 31467333, 2019).
polycystic ovary syndrome (1 paper, 2024). A disorder that manifests as multiple cysts on the ovaries. "One of the conducted toxicogenomic studies which assessed the link between PFAS mixtures and polycystic ovary syndrome (PCOS) found 74 genes linked to both PFAS exposure and PCOS, highlighting cell cycle regulation and steroid hormone synthesis—particularly genes like CCNB1 and SRD5A1." (PMID 39596398, 2024).